MLXIP (MLX interacting protein)
Description:
Binds DNA as a heterodimer with MLX and activates transcription. Binds to the canonical E box sequence 5'-CACGTG-3'. Plays a role in transcriptional activation of glycolytic target genes. Involved in glucose-responsive gene regulation.
Synonyms: bHLHe36; KIAA0867; MIR; MONDOA
Tractability: PROTAC: ubiquitination databases record sites on it.
Gene: Protein-coding gene on chromosome 12 (122,078,666 to 122,147,344, forward strand). Ensembl gene ENSG00000175727.
Subcellular location: Cytoplasm; Nucleus; Mitochondrion outer membrane
Gene Ontology:
Molecular function: DNA-binding transcription activator activity, RNA polymerase II-specific; RNA polymerase II transcription regulatory region sequence-specific DNA binding; DNA-binding transcription factor activity, RNA polymerase II-specific; RNA polymerase II cis-regulatory region sequence-specific DNA binding; protein dimerization activity
Biological process: positive regulation of transcription by RNA polymerase II; glucose homeostasis; regulation of transcription by RNA polymerase II
Cellular component: cytoplasm; mitochondrial outer membrane; nucleus; chromatin; RNA polymerase II transcription regulator complex
Genetic constraint (gnomAD): Loss-of-function variants: 28 observed, 83.25 expected, observed/expected ratio (o/e) 0.34, 90% interval 0.25 to 0.46. The upper end of that interval is the gene's LOEUF score, 0.46, which puts it in group 2 of 6, group 1 being the genes least tolerant of losing a copy. Missense variants: 911 observed, 1,148.6 expected, observed/expected ratio (o/e) 0.79, 90% interval 0.75 to 0.84. Synonymous variants: 484 observed, 477.3 expected, observed/expected ratio (o/e) 1.01, 90% interval 0.94 to 1.09.
Homologues: Orthologues: chimpanzee MLXIP (99% identical), macaque MLXIP (95% identical), dog MLXIP (90% identical), pig MLXIP (89% identical), rabbit MLXIP (89% identical), mouse Mlxip (87% identical), rat Mlxip (86% identical), guinea pig MLXIP (84% identical), tropical clawed frog mlxip (56% identical), zebrafish mlxip (50% identical), Drosophila melanogaster Mondo (29% identical), Caenorhabditis elegans mml-1 (24% identical). Paralogues in human: MLXIPL (39% identical), MLX (9% identical), TFAP4 (8% identical).
Diseases named in the same sentence as MLXIP in open-access papers:
MLXIP is named in the same sentence as 31 diseases in open-access papers, as found by Europe PMC text mining. Sharing a sentence is not in itself a finding about the gene and the disease. The quoted sentences say what the papers report.
Insulin resistance (9 papers, 2019 to 2024). Increased resistance towards insulin, that is, diminished effectiveness of insulin in reducing blood glucose levels. "MLXIP expression has also been implicated in the development of metabolic diseases such as obesity, insulin resistance, and T2DM." (PMID 38203607, 2023).
diabetes (5 papers, 2013 to 2025). "Furthermore, the association between MLXIP SNP and CHD was still significant after performing statistical adjustments (for age, sex, Diabetes and lipid levels)." (PMID 23840567, 2013).
neuroblastoma (4 papers, 2018 to 2023). Neuroblastoma (NB) is the most common solid, extracranial childhood tumor. "MYCN transcriptionally upregulates the expression of MondoA (also known as MLXIP) in neuroblastoma cells, which is a member of the extended MYC network with a role in regulation of cellular metabolism." (PMID 36077650, 2022). "In a neuroblastoma cell line, MYC-MAX and MLXIP-MLX were found to cooperatively regulate transcription of a subset of genes involved in metabolism." (PMID 30054853, 2018). "Detailed analysis remains to be carried out on cooperative binding by different network heterodimers, but initial work supports the idea that MYCN-MAX and MLXIP-MLX can co-occupy the TXNIP promoter region and act to cooperatively augment TXNIP expression in MYC-driven neuroblastoma." (PMID 30054853, 2018).
epilepsy (1 paper, 2015). A brain disorder characterized by episodes of abnormally increased neuronal discharge resulting in transient episodes of sensory or motor neurological dysfunction, or psychic dysfunction.
osteoarthritis (1 paper, 2023). A noninflammatory degenerative joint disease occurring chiefly in older persons, characterized by degeneration of the articular cartilage, hypertrophy of bone at the margins and changes in the synovial membrane. "Studies have shown that the MLXIP gene is involved in various biological processes, including glucose metabolism, lipid metabolism, and cellular senescence, which have also been implicated in the pathogenesis of osteoarthritis." (PMID 37749624, 2023).
cancer (17 papers, 2010 to 2024). A tumor composed of atypical neoplastic, often pleomorphic cells that invade other tissues. "Among these, WDR66, SETD1B, and MLXIP were novel markers for cancer metastasis and involved in epithelial-mesenchymal transition (EMT) 65-67." (PMID 36632223, 2023). "If MLXIP-MLX functions to suppress stress in MYC-driven cancers we might anticipate its involvement in other forms of stress response." (PMID 30054853, 2018).
tumor (9 papers, 2010 to 2025). "Recently, Wang reported that PRMT1 activates related pathways by recruiting MLXIP to the promoter region of β-catenin and thus plays a role in promoting tumor cell growth and metastasis." (PMID 40858547, 2025). "The resulting metabolic stress and cell death can be rescued by either restoring MLXIP expression, or by addition of the C18.1 monounsaturated fatty acid, oleate, supporting a critical role for lipid production in the survival of these tumor cells." (PMID 30054853, 2018).
MLXIP also shares sentences with these, for which no sentence is quoted: lactic acidosis (4 papers); metabolic disease (4); Obesity (4); melanoma (3); lymphoma (2); angiosarcoma (1); blood cancers (1); breast carcinoma (1); breast tumors (1); childhood cancers (1); colorectal cancer (1); diabetic retinopathy (1); gout (1); Hypertension (1); infection (1); Infertility (1); latent infection (1); metabolic syndrome (1); mucosal (1); Nonalcoholic fatty liver disease (1); prostate carcinoma (1); sarcoma (1); steatosis (1); sterility (1).